IGFBP1 (insulin like growth factor binding protein 1)
Diseases named in the same sentence as IGFBP1 in open-access papers (continued):
Sharing a sentence is not in itself a finding about the gene and the disease.
acute myocardial infarction (5 papers, 2021 to 2024). Necrosis of the myocardium, as a result of interruption of the blood supply to the area. "In another study of acute myocardial infarction (n = 34, mean 34 y, 17% F), lower IGFBP-1 and higher easily dissociable IGF-I and IGFBP-3 levels were observed, compared to age- and sex-matched controls." (PMID 39595651, 2024). "In T2D patients surviving acute myocardial infarction (n = 1253, mean 70 y, 33% F), higher levels of IGFBP-1 at admission predicted cardiovascular morbidity and mortality during a median follow-up of two years." (PMID 39595651, 2024). "Excessive Insulin-like growth factor binding protein-1 (IGFBP-1) amounts are considered to harm cardiomyocytes in acute myocardial infarction." (PMID 34531382, 2021). "Other studies indicated that IGFBP-1 is a long-term predictor of HF in survivors of a first acute myocardial infarction and predicts adverse clinical outcomes during outpatient follow-up of patients with chronic HF." (PMID 35127852, 2021). "In order to understand the effect of sh-IGFBP-1 on myocardial infarction, we performed TTC staining to observe the infarct size." (PMID 34531382, 2021). "Higher IGFBP-1 in acute myocardial infarction was associated with all-cause mortality but not with cardiovascular events over a median follow-up of 12 years (n = 180, median 64 y, 31% F)." (PMID 39595651, 2024). "In a small study in the acute phase after myocardial infarction (MI), s-IGFBP-1 was significantly lower in MI patients (n = 34) than in healthy controls (n = 17), indicating that low s-IGFBP-1 may be harmful." (PMID 37298072, 2023). "Moreover, the heart mainly manifests as myocardial fibrosis after 28 days after myocardial infarction, and knocking down of IGFBP-1 has a certain therapeutic effect on cardiac function and reduces cardiac fibrosis after 28 days of myocardial infarction." (PMID 34531382, 2021). "In order to find out whether knockdown of IGFBP-1 has a potential therapeutic effect on myocardial infarction, we maintained injected animals for 28 days after LAD ligation and assessed cardiac function by ultrasound examination." (PMID 34531382, 2021).
chronic kidney disease (5 papers, 2011 to 2020). Impairment of the renal function secondary to chronic kidney damage persisting for three or more months. "The etiology of growth delay in children with chronic kidney disease is multifactorial, including rickets, GH resistance, reduced GH secretion rate or greater loss of GH, functional IGF deficiency and increased IGFBP -1,-2,-4 and -6." (PMID 21859490, 2011). "IGFBPs not only enhance the effects of IGFs, but also have IGF-independent activities; for instance, IGFBP1 and IGFBP6 levels increase in chronic renal failure." (PMID 30608957, 2019).
ischemia (5 papers, 2020 to 2025). A hypoperfusion of the BLOOD through an organ or tissue caused by a PATHOLOGIC CONSTRICTION or obstruction of its BLOOD VESSELS, or an absence of BLOOD CIRCULATION. "Overall, in vivo studies show that loss of IGFBP-1 plays a causal role in the development of cardiometabolic disorders, while increasing IGFBP-1 promotes neovascularization in response to ischemia." (PMID 40710778, 2025). "Immunohistochemical staining confirmed that IGFBP-1 silencing protected the heart tissue by reducing the protein amounts of Bax upon ischemia." (PMID 34531382, 2021). "IGFBP1 is promoted by LEN-induced ischemia, and it could induce neo-angiogenesis in a VEGF-independent manner." (PMID 37762018, 2023). "In mice with intact insulin signaling, neither IGFBP-1 knockout nor overexpression altered recovery of tissue perfusion after induction of hindlimb ischemia." (PMID 32190801, 2020). "Irrespective of whether loss of IGFBP-1 plays a causal role in the development of cardiometabolic disorders, increasing IGFBP-1 levels appears effective in promoting neovascularization in response to ischemia." (PMID 32190801, 2020).
prediabetes (5 papers, 2020 to 2024). "Accordingly, high IGFBP-1 levels were also shown to identify people with prediabetes who are unresponsive to standard lifestyle interventions." (PMID 38928106, 2024). "For example, a study reported that low IGFBP2 was the strongest predictor for prediabetes (OR: 7.5) in women, while in men, the strongest predictor was IGFBP1 (OR: 13.4)." (PMID 39458471, 2024). "Insulin-like growth factor 1 (IGF- 1) and Insulin-like growth factor binding protein 1(IGFBP-1) were shown to predict T2DM onset in prediabetes." (PMID 38928106, 2024). "In women the strongest predictor for T2D was adiponectin and in men IGFBP-1, and for prediabetes IGFBP-2 in women and IGFBP-1 in men." (PMID 36686443, 2022). "For the prediction of prediabetes, only IGFBP-1 (OR:13.44) and IGFBP-2 (OR:4.03) yielded significant ORs." (PMID 36686443, 2022). "High serum levels of free IGF-I levels have indeed been shown to predict AGT, which is in line with our findings of high total IGF-I (positively correlated with free IGF-I) and low IGFBP-1 (negatively correlated with free IGF-I) as predictors of prediabetes and T2D in women." (PMID 36686443, 2022). "The strongest predictor for prediabetes was in men low IGFBP-1 and in women low IGFBP-2." (PMID 36686443, 2022). "In men, low IGFBP-1 was the strongest predictor for both prediabetes (OR:13.4) and T2D (OR:14.9)." (PMID 36686443, 2022). "As for women, levels of adiponectin, IGFBP-1 and IGFBP-2 were significantly lower at baseline in those who later developed prediabetes or T2D as compared to controls." (PMID 36686443, 2022). "Conversely, baseline levels of adiponectin, IGFBP-1 and IGFBP-2 were significantly lower in individuals, who later developed prediabetes or T2D compared to the controls." (PMID 36686443, 2022). "In contrast to our findings in women, the strongest predictor of both prediabetes and T2D in NGT men was a low fasting IGFBP-1." (PMID 36686443, 2022). "In those with prediabetes or T2DM (n = 74), HbA1c at 2 years correlated to baseline BMI (r = -0.27, p = 0.028), age (r = 0.43, p < 0.001), HbA1c (r = 0.37, p = 0.001) and IGFBP-1 (r = 0.25, p = 0.038), and was normalized in 45/74 (61%) at 1 year and in 36 subjects (49%) at 2 years." (PMID 32934313, 2020). "The increase in mean IGFBP-1 and adiponectin levels 1 year after RYGB to normal levels suggest reduced hepatic inuslin resistance, improved insulin sensitivity and protection against future prediabetes and/or T2DM in those with normal glucose levels and prediabetes." (PMID 32934313, 2020).
chorioamnionitis (4 papers, 2007 to 2023). A morphologic finding indicating inflammation of the fetal sac membranes. "It is postulated that with the progression of acute histologic chorioamnionitis, there is a decrease in the level of the intact form of insulin-like growth factor binding protein 1, ultimately affecting IGF-1 bioavailability." (PMID 36911032, 2023). "Previously, a 11-kDa proteolytic fragment of the insulin-like growth factor binding protein 1 (IGFBP1) protein was reported to be up-regulated in the amniotic fluid and maternal serum of pregnant women with intra-amniotic infection." (PMID 22496790, 2012). "To date, several studies have identified maternal blood biomarkers that are predictive of histological chorioamnionitis, including various host proteins secreted in response to microbial pathogens, such as serum CRP, MMP-9, IL-6, S100 calcium-binding proteins A8/A9 and IGFBP-1." (PMID 34046191, 2021).
depression (4 papers, 2016 to 2023). "It concluded that exercise was beneficial for BC survivors because it improved the QoL, body configuration, and muscle strength, decreased serum levels of insulin, IGF-II, and IGFBP-1, and alleviated depression and anxiety." (PMID 31759342, 2019). "Previous studies have compared the proteomic profiles of depressed patients and healthy controls, finding that in atypical depression, but not melancholic, both IGFBP-1 and IGFBP-2 were significantly decreased." (PMID 37894932, 2023).
esophageal cancer (4 papers, 2020 to 2025). A primary or metastatic malignant neoplasm involving the esophagus. "Previous observational research has highlighted an association between IGFBP-1 levels or genetic polymorphisms and esophageal cancer risk." (PMID 40987470, 2025). "Loss of IGFBP1-5 expression was frequently found in esophageal cancer cells, while IGFBP6 was expressed in all cell lines (data not show)." (PMID 32041673, 2020). "IGFBP1 was identified as a promising biomarker for the diagnosis of early-stage esophageal cancer in a clinical study involving 2028 patients with esophageal cancer at three medical centers." (PMID 36761024, 2023). "In this study, using public databases and our clinical cohorts, we found the genes IGFBP1 and WNT3A from WNT signaling, which are closely associated with immunotherapy for esophageal cancer." (PMID 36358276, 2022). "Multifactorial Cox regression analysis indicated that gender, TNM stage, IGFBP1 and the IGFBP1hiWNT3Alo signature (p = 0.010; HR 0.520; 95% CI 0.380–0.803) was an independent predictor of prognosis in esophageal cancer." (PMID 36358276, 2022). "We further evaluated IGFBP1-6 expression in esophageal cancer cells by RT-PCR." (PMID 32041673, 2020). "However, there have been few biological studies on IGFBP-1 in esophageal cancer." (PMID 36761024, 2023).
Hypoinsulinemia (4 papers, 2020 to 2024). A decreased concentration of insulin in the blood. "While the fetus at high altitude does not face hypoxia, IGFBP-1 is normally inhibited by insulin, and so the hypoinsulinemia that the fetus faces at high altitude may allow the IGFBP-1 level to rise and induce FGR in a similar manner." (PMID 38694168, 2024). "Conversely, during prolonged intra-portal hypoinsulinemia (e.g., malnutrition, anorexia nervosa, and T1D), IGFBP-1 levels increase several-fold, leading to the increased complex formation between IGF-I and IGFBP-1 and clear reductions in free IGF-I (“brake” effect)." (PMID 39665021, 2024).
leukemia (4 papers, 2020 to 2025). A malignant (clonal) hematologic disorder, involving hematopoietic stem cells and characterized by the presence of primitive or atypical myeloid or lymphoid cells in the bone marrow and the blood. "The results of this study indicated that leukemia cells hijack host glucose by inducing IGFBP1 production from adipose tissue to mediate insulin sensitivity and by inducing gut dysbiosis, serotonin loss, and incretin inactivation to suppress insulin secretion." (PMID 37190210, 2023). "Disrupting this adaptive homeostasis attenuates leukemia progression, and that SCFAs inhibit leukemia-induced adaptive homeostasis by affecting the integrity of the intestinal epithelium and regulating IGFBP1 as well as insulin levels." (PMID 37190210, 2023). "In other diseases such as leukemia, IGFBP1 is also abnormally elevated, which contributes to increased lipolysis in WAT and systemic insulin resistance." (PMID 35927268, 2022). "Neutralization of IGFBP1 also decreases lipolysis in WAT of leukemia mouse model." (PMID 35927268, 2022).
liver disease (4 papers, 2019 to 2025). "This protein is known to possess a hepatoprotective role; IGFBP-1 is among the first genes to be overexpressed after a partial hepatectomy, and it also increases during liver disease." (PMID 38541155, 2024). "Since the suppression of IGFBP-1 expression by taurine may be linked to its ability to reduce senescent cells, future studies are required to clarify whether IGFBP-1 promotes liver cell senescence and/or exacerbates liver disease." (PMID 40286436, 2025).
liver fibrosis (4 papers, 2022 to 2025). "A pilot study found that there was a close relationship between serum IGF-1 and IGFBP-1 levels and advancement of liver fibrosis of NAFLD." (PMID 38041076, 2023). "SPP2 may interact with insulin-like growth factor binding protein 1 (IGFBP1), potentially inhibiting the progression of liver fibrosis and cirrhosis." (PMID 40052788, 2025).
lung adenocarcinoma (4 papers, 2021 to 2025). A carcinoma that arises from the lung and is characterized by the presence of malignant glandular epithelial cells. "In lung adenocarcinoma cell lines where elevated IGFBP-1 correlates with reduced survival, knockout of IGFBP-1 significantly reduces cell proliferation and migratory potential in vitro." (PMID 41226289, 2025). "To determine the role of IGFBP1 in tumor cell migration, we depleted endogenous IGFBP1 with shRNA in A549 lung adenocarcinoma cells and rescued the cells with shRNA‐resistant (r) IGFBP1." (PMID 37296072, 2023). "The expression of IGFBP1 is closely related to the overall prognosis of non-small cell lung cancer (NSCLC), especially patients with lung adenocarcinoma." (PMID 35903696, 2022). "Moreover, immunohistochemistry (IHC) analysis of IGFBP1 expression in primary tumors from lung adenocarcinoma patients with or without metastatic recurrence further confirmed that the tumors from the patients with recurrence had higher expression of IGFBP1 than those from the patients without." (PMID 37296072, 2023).
malnutrition (4 papers, 2008 to 2024). Inadequate nutrition resulting from poor diet, malabsorption, or abnormal nutrient distribution. "In humans and mice, IGFBP-1 is highly induced by a variety of catabolic conditions, including fasting, malnutrition, and endoplasmic reticulum stress." (PMID 18769480, 2008). "IGFBP-1 is highly inducible under a variety of catabolic conditions such as food deprivation, malnutrition, stress, injury, endoplasmic reticulum stress, and hypoxia." (PMID 18769480, 2008). "The decreased IGF-I level co-existing with elevated IGFBP-1 level in the smoking mother group may reflect malnutrition and can indicate a low metabolic rate in their offspring." (PMID 32635165, 2020). "Fasting or malnutrition have been shown to increase the synthesis of IGFBP-1 in a non-pregnant population." (PMID 32923723, 2020).
osteoarthritis (4 papers, 2021 to 2026). A noninflammatory degenerative joint disease occurring chiefly in older persons, characterized by degeneration of the articular cartilage, hypertrophy of bone at the margins and changes in the synovial membrane. "Whether variations in IGFBP-1 levels in aseptic loosening are associated with osteoarthritis needs to be assessed by including age- and sex-matched patients without osteoarthritis." (PMID 33436773, 2021).
placental insufficiency (4 papers, 2018 to 2024). Failure of the placenta to deliver an adequate supply of nutrients and oxygen to the fetus. "Fetal hepatocytes cultured under hypoxic conditions undergo a 2.5-fold and 3-fold increase in IGFBP-1 and IGFBP-3 levels, respectively, leading to suggestions that this is the molecular cause for FGR resulting from placental insufficiency." (PMID 38694168, 2024). "We propose that decidual mTORC1 links oxygen availability and IGF-1 signaling to placental insufficiency and impaired fetal growth by regulating IGFBP-1 secretion and phosphorylation." (PMID 34572595, 2021). "In addition, the levels of fetal insulin-like growth factor-binding protein-1 (IGFBP-1) were elevated in PM; this molecule negatively regulates IGFs expression and is associated with placental insufficiency." (PMID 34867919, 2021).
alcoholic liver diseases (3 papers, 2017 to 2025). A disorder caused by damage to the liver parenchyma due to alcohol consumption. "IGFBP-1 expression is correlated with increased senescent cell burden in non-alcoholic liver disease model." (PMID 40286436, 2025). "It has been reported that IGFBP-1 is induced in conditions such as alcoholic and non-alcoholic liver diseases." (PMID 40286436, 2025).
atrial fibrillation (3 papers, 2021 to 2024). A disorder characterized by an electrocardiographic finding of a supraventricular arrhythmia characterized by the replacement of consistent P waves by rapid oscillations or fibrillatory waves that vary in size, shape and timing and are accompanied by an irregular ventricular response. "In another study of HF patients, IGFBP-1 was higher in those with atrial fibrillation (n = 648, mean 72 y, 25% F) compared to patients in sinus rhythm (n = 972, mean 65 y, 31% F)." (PMID 39595651, 2024). "In a cohort study of individuals with HF (n = 3378, mean 62, 54% F), higher IGFBP-1 and lower IGF-I concentrations were associated with a higher risk of incident atrial fibrillation over a mean follow-up of 12 years." (PMID 39595651, 2024). "Multivariable Cox regression showed that IGF-1 levels, IGFBP-1 levels, and IGFBP-1/IGF-1 ratio were not predictive of prognosis after adjusting for age, gender, atrial fibrillation, and NT-proBNP in patients with HF." (PMID 35127852, 2021).
COVID-19 (3 papers, 2021 to 2024). A disease caused by infection with severe acute respiratory syndrome coronavirus 2. "Finally, a total of eleven differential factors related to COVID-19 disease severity were identified, including: TRAIL R1, IGFBP-1, IGFBP-4, VCAM-1, sFRP-3, FABP2, Transferrin, GDF15, IL-1F7 (also known as IL-37), IL-5Rα, and CD200." (PMID 34335566, 2021). "Furthermore, IGFBP-1, IL-16, macrophage colony-stimulating factor (M-CSF), and VCAM-1 positively correlated with SOFA- and WHO scores, representing the contribution of the endothelium to severe COVID-19." (PMID 34893580, 2021).
ischemic stroke (3 papers, 2023 to 2024). A stroke disorder caused by obstruction of blood flow to the brain, due to thrombotic (local blood clot formation) or embolic (due to a blood clot or other material traveling from another site) event. "In alignment with the other Cox proportional hazards regression analyses, we performed analyses of whether log IGFBP-1 was associated with mortality in the main subtypes of ischemic stroke." (PMID 37298072, 2023). "Our observations are in line with previous reports showing that IGF1/IGFBP1 intranasal delivery is protective after ischemic stroke." (PMID 38769116, 2024). "Future studies should focus on investigating s-IGFBP-1 in relation to temporal profiles with repeated blood samples located in the subacute phase after ischemic stroke, and regarding modalities of outcome in the long-term perspective and preferably also include data on the cause of death." (PMID 37298072, 2023). "However, the role of serum IGFBP-1 (s-IGFBP-1) after ischemic stroke is unclear." (PMID 37298072, 2023). "Therefore, we investigated ischemic stroke patients from the Sahlgrenska Academy Study on Ischemic Stroke (SAHLSIS) cohort, regarding relationships between BMI, s-IGFBP-1, HOMA-IR, and functional outcome evaluated by modified Ranking scale (mRS) at poststroke follow-up at 7 years." (PMID 38732147, 2024).
macrosomia (3 papers, 2020 to 2025). "The IGF-1/IGFBP-1 ratio was also positively associated with macrosomia in all four groups." (PMID 37685292, 2023). "IGFBP-2 and IGFBP-5 emerged as significant independent predictors of LGA birth in adjusted models (OR = 2.515 and 2.402, respectively; p < 0.001), consistent with prior studies linking first-trimester IGF-1 and IGF-1/IGFBP-1 ratios to macrosomia." (PMID 40943286, 2025). "A study found that higher first-trimester IGF-1 and lower IGFBP-1 are associated with macrosomia in both diabetic and nondiabetic pregnancies." (PMID 37685292, 2023).
metastatic tumors (3 papers, 2016 to 2025). "Within this list of genes in the metastatic tumor dataset, individual genes such as TMEM45A, IGFBP1, IGFBP5, and MALAT1 appeared to be associated with a worse patient survival." (PMID 40241258, 2025). "The level of IGFBP1 was also validated in the metastatic tumors by IHC staining." (PMID 37296072, 2023). "Regarding the specificity of these genes in metastatic tumors, the expression levels of ALDH1A1 and IGFBP1 were increased by 15.6% and 6.3%, respectively, compared with normal liver tissues, considering a contamination rate of <3%." (PMID 27152521, 2016).